COL17A1 (collagen type XVII alpha 1 chain)
Description:
May play a role in the integrity of hemidesmosome and the attachment of basal keratinocytes to the underlying basement membrane. The 120 kDa linear IgA disease antigen is an anchoring filament component involved in dermal-epidermal cohesion. Is the target of linear IgA bullous dermatosis autoantibodies.
Synonyms: LAD-1; BP180; BPAG2; BA16H23.2; BPA-2; ERED; JEB4
Tractability: Antibody: its Gene Ontology location is reachable by antibodies, with high confidence; UniProt places it where antibodies can reach, with medium confidence; UniProt predicts a signal peptide or a membrane-spanning region; the Human Protein Atlas places it where antibodies can reach. PROTAC: ubiquitination databases record sites on it.
Gene: Protein-coding gene on chromosome 10 (104,030,753 to 104,086,225, reverse strand). Ensembl gene ENSG00000065618.
Subcellular location: Cell junction, hemidesmosome; Membrane; Secreted, extracellular space, extracellular matrix, basement membrane (120 kDa linear IgA disease antigen); Secreted, extracellular space, extracellular matrix, basement membrane (97 kDa linear IgA disease antigen)
Subcellular location (Human Protein Atlas): Plasma membrane; Golgi apparatus; Predicted to be secreted
Pathways (Reactome):
Extracellular matrix organization: Assembly of collagen fibrils and other multimeric structures; Collagen biosynthesis and modifying enzymes; Collagen chain trimerization; Collagen degradation
Cell-Cell communication: Type I hemidesmosome assembly
Immune System: Immunoregulatory interactions between a Lymphoid and a non-Lymphoid cell
Gene Ontology:
Molecular function: extracellular matrix structural constituent conferring tensile strength; protein binding
Biological process: hemidesmosome assembly; cell-matrix adhesion; epidermis development; extracellular matrix organization
Cellular component: extracellular matrix; hemidesmosome; plasma membrane; cell-cell junction; collagen type XVII trimer; endoplasmic reticulum lumen; extracellular region; basement membrane; membrane
Genetic constraint (gnomAD): Loss-of-function variants: 180 observed, 224.15 expected, observed/expected ratio (o/e) 0.8, 90% interval 0.71 to 0.91. The upper end of that interval is the gene's LOEUF score, 0.91, which puts it in group 3 of 6, group 1 being the genes least tolerant of losing a copy. Missense variants: 1,908 observed, 2,006.1 expected, observed/expected ratio (o/e) 0.95, 90% interval 0.92 to 0.99. Synonymous variants: 719 observed, 748.58 expected, observed/expected ratio (o/e) 0.96, 90% interval 0.9 to 1.02.
Homologues: Orthologues: chimpanzee COL17A1 (99% identical), macaque COL17A1 (91% identical), pig COL17A1 (85% identical), rabbit COL17A1 (80% identical), rat Col17a1 (80% identical), mouse Col17a1 (80% identical), dog COL17A1 (79% identical), guinea pig COL17A1 (76% identical), zebrafish col19a1 (5% identical). Paralogues in human: COL11A1 (24% identical), COL5A1 (24% identical), COL18A1 (24% identical), COL4A5 (24% identical), COL2A1 (23% identical), COL11A2 (23% identical), COL1A1 (22% identical), COL5A2 (22% identical), COL3A1 (22% identical), COL4A1 (22% identical), COL4A4 (22% identical), COL5A3 (22% identical), and 25 more.
Diseases named in the same sentence as COL17A1 in open-access papers:
COL17A1 is named in the same sentence as 144 diseases in open-access papers, as found by Europe PMC text mining. Sharing a sentence is not in itself a finding about the gene and the disease. The quoted sentences say what the papers report.
bullous pemphigoid (118 papers, 2006 to 2026). Bullous pemphigoid (BP) is the most common form of autoimmune bullous dermatosis. "Bullous pemphigoid (BP) is an autoimmune blistering disease caused by autoantibodies to collagen type 17 (COL17A1) and is a recognized immune-related adverse event in patients receiving immune checkpoint inhibitors (ICIs)." (PMID 41658267, 2026). "COL7A1 mutations lead to epidermolysis bullosa, and COL17A1 mutations cause bullous pemphigoid." (PMID 37800682, 2023). "Bullous pemphigoid is the most common autoimmune subepidermal blistering disease and is characterized by the production of autoantibodies that directly target the bullous pemphigoid antigen 180 (BP180 or COL17A1) within the dermoepidermal junction (DEJ)." (PMID 30473747, 2018).
pemphigoid (40 papers, 2011 to 2026). "COL17A1 maintains hemidesmosome integrity and is the direct target of autoantibody in bullous dermatosis." (PMID 31612115, 2019).
junctional epidermolysis bullosa (19 papers, 2012 to 2025). "Loss of function variants in COL17A1 lead to junctional epidermolysis bullosa (JEB) in human patients." (PMID 37895184, 2023). "Previous work strongly implicated Collagen 17a1 (Col17a1) as a potent genetic modifier of junctional epidermolysis bullosa (JEB) caused by a hypomorphic mutation (Lamc2jeb) in mice." (PMID 37796769, 2023). "CRISPR/Cas9-induced homology-directed repair (HDR) represents a promising tool for editing causal mutations in COL17A1 in the treatment of junctional epidermolysis bullosa (JEB)." (PMID 36091706, 2022). "Collagen XVII is most typically associated with human disease when biallelic COL17A1 variants (>230) cause junctional epidermolysis bullosa (JEB), a rare, genetically heterogeneous, mucocutaneous blistering disease with amelogenesis imperfecta (AI), a developmental enamel defect." (PMID 37979963, 2024). "Junctional epidermolysis bullosa (JEB) is a hereditary disease that may be caused by mutations in the COL17A1 gene, coding for type XVII collagen α1 chain [α1(XVII)]." (PMID 38928229, 2024). "For example, mutations in the COL17A1 gene can cause junctional epidermolysis bullosa (JEB)." (PMID 37803411, 2023). "Moreover, COL17A1 deficiency is associated with junctional epidermolysis bullosa, a severe skin disease characterised by hair loss." (PMID 28228108, 2017). "Similar to DEB, junctional epidermolysis bullosa (JEB) can result from pathogenic variants in the COL17A1 gene, which encodes type XVII collagen." (PMID 40790091, 2025). "In addition to pemphigoid diseases, BP180 is also associated with genetic blistering skin diseases: missense or nonsense mutations in the COL17A1 gene are found in patients with one subtype of junctional epidermolysis bullosa (JEB)." (PMID 34830116, 2021). "Such an instability could well contribute to the disease mechanism in human patients and has been reported to be involved for mutations in COL2A1 causing Kniest dysplasia, in COL3A1 causing Ehlers-Danlos syndrome type IV and in COL17A1 causing junctional epidermolysis bullosa." (PMID 29439465, 2018). "Mutations in LAMA3, LAMC2, COL17A1, ITGA6, and ITGB4 are associated with the blistering skin disorder junctional epidermolysis bullosa and cause severe enamel hypoplasia, grooves and enamel pitting." (PMID 31417410, 2019). "Similarly, junctional epidermolysis bullosa (JEB) results from mutations in the LAMA3, LAMB3, LAMC2, and COL17A1 genes, which lead to defects in the production of laminin 332, an important protein to help attach the epidermis to the dermis." (PMID 30783081, 2019). "This theory is proven in patients with junctional epidermolysis bullosa (JEB), a disorder characterized by mutations in the COL17A1 gene resulting in the absence of collagen XVII or expression of a structurally altered protein leading to subepidermal blistering and immature HDs." (PMID 32266137, 2020). "These same genes, under an autosomal recessive inheritance transmission are responsible for various forms of epidermolysis bullosa (EB: Non-Herlitz junctional epidermolysis bullosa (nH-JEB) COL17A1; recessive dystrophic epidermolysis bullosa (RDEB) COL7A1; junctional EB (JEB) LAMA3, LAMB3, LAMC2)." (PMID 37228816, 2023).
epidermolysis bullosa (16 papers, 2010 to 2025). Epidermolysis bullosa (EB) is a group of genetic skin diseases that cause the skin to blister very easily. "In Family 6, a nonsense variant c.1394G>A (p.Trp465*) was identified in the COL17A1 gene (NM_000494.4), consistent with junctional epidermolysis bullosa." (PMID 40956805, 2025). "Mutations of LAMA3, LAMB3, LAMC2, DST, and COL17A1 have been reported in heritable skin fragility disorders and epidermolysis bullosa (EB)." (PMID 36430582, 2022). "The dystrophic forms of epidermolysis bullosa (EB) with mutations in COL7A1 or COL17A1 gene is one of the major forms of EB where patients present a fragile skin, which can shed at the slightest touch." (PMID 29738498, 2018). "Many promising results have been published using the CRISPR/Cas9 technology to efficiently correct mutations in epidermolysis bullosa, especially for mutations in COL7A1, COL17A1, KRT5 and KRT14." (PMID 36901775, 2023). "The Lamc2jeb junctional epidermolysis bullosa (EB) mouse model has been used to demonstrate that significant genetic modification of EB symptoms is possible, identifying as modifiers Col17a1 and six other quantitative trait loci, several with strong candidate genes including dystonin (Dst/Bpag1)." (PMID 37883475, 2023). "For example, COL17A1 encoding collagen type XVII, alpha 1 (located 529,5 Kb from the significant marker rs110088444, on BTA 26) is involved in epidermolysis bullosa, causing separation of the basal keratinocyte from the underlying basement membrane and consequently skin atrophy." (PMID 25585689, 2015). "Both COL17A1 and COL7A1 are involved in Epidermolysis Bullosa." (PMID 37414817, 2023).
pancreatic cancer (16 papers, 2017 to 2025). "COL17A1, which encodes for collagen XVII, has been linked to pancreatic cancer; studies have shown that high levels of COL17A1 expression are associated with a poor prognosis for pancreatic cancer patients." (PMID 40770187, 2025). "COL17A1 is upregulated in pancreatic cancer and positively associated with poor prognosis." (PMID 31612115, 2019). "Moreover, a high expression of type 17 collagen alpha 1 chain (COL17A1) may be associated with a positive course for breast cancer patients, while it could be an unfavorable prognostic marker for pancreatic cancer patients." (PMID 39769286, 2024). "This particular subset exhibited elevated expression of COL17A1 (collagen type XVII alpha 1 chain), LAMB3 (laminin subunit beta-3) and other genes associated with tumor progression and worse prognosis in pancreatic cancer." (PMID 40092486, 2025). "COL17A1, a transmembrane collagen protein, facilitated tumour growth and predicted poor prognosis in pancreatic cancer and regulated dormancy in human colon cancer stem cells." (PMID 39187937, 2024). "The scatterplots showed that, as the expression of COL17A1/GBP4/CDC6 increased and the risk score increased, the survival time of each pancreatic cancer patient decreased and the proportion of death increased." (PMID 39376555, 2024). "Of tumor-elevated proteins identified in LMD sampling, 4 additional tumor-associated proteins, COL17A1, VSNL1, LYPD3, and VCAN, were reported in the Pancreatic Cancer Database." (PMID 36266629, 2022). "Of 115 tumor-elevated proteins identified in LMD sampling, 4 additional tumor-associated proteins, COL17A1, VSNL1, LYPD3, and VCAN, were reported in the Pancreatic Cancer Database." (PMID 36266629, 2022). "Our data show that the expression of COL17A1 is very high in pancreatic cancer tissues and is closely related to the patients' overall survival time." (PMID 33381179, 2020). "Meanwhile, a previous study reported that COL17A1 could promote proliferation, migration, epithelial-mesenchymal transition of pancreatic cancer cells." (PMID 39376555, 2024). "Therefore, we subsequently focused on exploring the functions and mechanisms of PVT1, CDC6 and COL17A1 in pancreatic cancer." (PMID 39376555, 2024). "Our data also indicate that COL17A1 may mediate the inhibition of pancreatic cancer cells apoptosis by activating the NF-κB signaling pathway." (PMID 33381179, 2020). "Furthermore, we explored the correlation between COL17A1 expression and clinicopathological characteristics in pancreatic cancer and observed that the overexpression of COL17A1 in pancreatic adenocarcinoma patients is significantly correlated with overall survival (OS)." (PMID 33381179, 2020). "Furthermore, COL17A1 stimulates the EMT, migration, invasion, and proliferation of pancreatic cancer and is used as a diagnosis biomarker in both pancreatic cancer and lung cancer." (PMID 39682235, 2024). "Finally, COL17A1 can be used as a tumor biomarker, since serum COL17 levels were higher in patients with different solid tumors, including pancreatic cancer, compared to healthy controls." (PMID 39769286, 2024). "We also identified novel pancreatic cancer genes, such as SCML2, COL17A1, AMIGO2, PTPRR, suggesting our method might be able to predict novel PDAC-related genes." (PMID 28611293, 2017).
breast carcinoma (15 papers, 2015 to 2024). "Among the genes mutated only in recurrent tumors, COL17A1 has been shown to prevent breast cancer cell invasion and migration." (PMID 37761830, 2023). "The other variant with a very high CADD score was seen in the COL17A1 gene, which inhibits cell migration and invasion and is a favorable prognostic marker in breast cancer." (PMID 35625741, 2022). "The associations of COL17A1 expression and tumor progression were explored in breast cancer patients using data from the METABRIC study." (PMID 34293053, 2021). "Taken together, these analyses suggest that reduced COL17A1 expression in breast cancer is caused by hypermethylation of the COL17A1 promoter." (PMID 27891193, 2016). "In contrast, another study found that upregulation of COL17A1 expression was related to better prognosis in breast cancer." (PMID 36936416, 2023). "The high expression of COL17A1 gene encoding COL17 is associated with low-proliferation tumors, extended tumor-free period, and overall survival of breast cancer patients." (PMID 34293053, 2021). "In Addition, the COL17A1 level is an independent prognostic factor for better survival of breast cancer patients." (PMID 34293053, 2021). "Other metastases genes associated with poor prognosis in breast cancer, such as CEACAM6, COL17A1, CXCL8, TNFAIP3, SEMA7A and L1CAM, are also attenuated with SP receptor antagonist treatment." (PMID 34359773, 2021). "Taken together, our results implicate a role of COL17 in suppressing breast cancer cell migration and invasion, whereby a high level of COL17A1 expression leads to a better prognosis of patients with breast invasive carcinoma." (PMID 28915553, 2017). "We further analyzed the relationship between COL17A1 expression and tumor progression in breast cancer patients using TCGA data." (PMID 28915553, 2017). "In cervical cancer, the COL17A1 locus was less frequently subject to copy number changes than in breast cancer." (PMID 27891193, 2016). "Immunohistochemistry on ductal breast cancers confirmed that the COL17A1 protein product, collagen XVII, is underexpressed." (PMID 27891193, 2016). "While the majority of the breast cancers (61% (657/1075)) had retained two copies of the COL17A1 locus, nearly a third, 31% (329/1075), lost one or both alleles." (PMID 27891193, 2016). "We observed that COL17A1 is underexpressed in breast cancer and overexpressed in cervical and other epithelial cancers." (PMID 27891193, 2016). "In breast cancer, COL17A1 is hypermethylated and downregulated." (PMID 31612115, 2019). "The hyper-methylation of COL17A1 promoter increased ductal breast cancer metastasis." (PMID 29340021, 2017). "COL17A1 expression is particularly low in metastatic breast cancer cells." (PMID 28915553, 2017). "Hence, we compared the COL17A1 promoter methylation status in normal breast and breast cancer samples using TCGA DNA methylation data." (PMID 27891193, 2016).
breast carcinoma (continued). "Interestingly, consistent with the opposed direction of misexpression in these cancers, the COL17A1 promoter is hypermethylated in breast cancer and hypomethylated in cervical cancer." (PMID 27891193, 2016). "Noteworthy, the CM1 list revealed a set of probes for which little literature exists in relation to breast cancer subtypes: CDCA5, CCL15, COL17A1, GLYATL2, ROPN1, LINC00993 and C6orf211." (PMID 26132585, 2015). "The lower proliferative capabilities of these MCF-7 cultures were consistent with elevated P21 gene expression and COL17A1, a marker of low proliferative potential in breast cancer cell lines (data not shown)." (PMID 39030607, 2024). "The observation that copy number changes do not have a major impact on COL17A1 expression levels in breast cancer suggests that additional mechanisms regulate this gene’s expression." (PMID 27891193, 2016). "Specifically, COL17A1 levels in breast carcinomas and lung adenocarcinomas are similar, while the COL17A1 levels are highest in normal breast tissue and lowest in normal lung tissue." (PMID 27891193, 2016).
melanoma (15 papers, 2010 to 2026). A malignant, usually aggressive tumor composed of atypical, neoplastic melanocytes. "Cutaneous squamous cell carcinoma and melanoma exhibited the highest COL17A1 mutation burden, whereas renal cell carcinoma had a low burden." (PMID 41658267, 2026). "Experiments in rodent models disclosed that truncation mutation of Col17A1 gene promoted melanoma and supported its progression through modulation of the skin tumor microenvironment by basal keratinocytes." (PMID 39267741, 2024). "Sequencing of COL17A1 from melanoma cDNA has revealed a series of aberrations that cause the post-translational degradation of the ectodomain and so its deficiency." (PMID 37547602, 2023). "COL17A1 was associated with pigmentation and melanocyte supply to the epidermis, and its accumulation in melanocytic tumors has been associated with malignant transformation, having been proposed as a potential target for antibody-induced melanoma apoptosis." (PMID 36614248, 2023). "Some of these genes had already been described in earlier studies as being down-regulated during melanoma progression: COL17A1, DSC3, KLK7, SLPI and KLK8, or over-expressed, e.g. CCL20, THBS1 and THBS4." (PMID 22032772, 2011). "Among these hub genes, we identified the attenuated expressions of CDH1, COL17A1, DSG1, KRT14, and FLG in melanoma metastases compared with primary melanoma via bioinformatics analysis upon the GSE8401 and TCGA datasets." (PMID 35054979, 2022). "COL17A1 was overexpressed in several cancers but underexpressed in melanoma, without strong correlation to tumor-infiltrating immune cells." (PMID 41658267, 2026). "In 2017, Patel used the CRISPR system, together with a machine-learning computational model, to identify genes essential for tumor progression in melanoma cell lines, such as collagen type XVII alpha 1 (COL17A1), twinfilin-1 (TWF1), microRNA 101-2 (Hsa-Mir-101-2) and ribosomal protein L23 (RPL23)." (PMID 39696697, 2024).